CD93 (CD93 molecule)
Description:
Cell surface receptor that plays a role in various physiological processes including inflammation, phagocytosis, and cell adhesion. Plays a role in phagocytosis and enhances the uptake of apoptotic cells and immune complexes by acting as a receptor for defense collagens including surfactant protein A/SFTPA1, C1q, and mannose-binding lectin (MBL2). Plays a role in the regulation of endothelial cell function and adhesion by activating angiogenesis. Mechanistically, exerts its angiogenic function by associating with beta-dystroglycan, leading to SRC-dependent phosphorylation and subsequent recruitment of CBL. In turn, CBL provides a docking site for downstream signaling components, such as CRKL to enhance cell migration. Participates in angiogenesis also by acting as a receptor for the ECM pan-endothelial glycoprotein multimerin-2/MMRN2 and IGFBP7 ligands. Both ligands play a non-redundant role in CD93-mediated endothelial cell function. Acts as a key regulator of endothelial barrier function through modulating VEGFR2 function (By similarity).
Synonyms: C1qR(p); C1qRp; C1QR1; MXRA4; dJ737E23.1; CDw93; ECSM3
Tractability: Antibody: UniProt places it where antibodies can reach, with high confidence; its Gene Ontology location is reachable by antibodies, with high confidence; UniProt predicts a signal peptide or a membrane-spanning region; the Human Protein Atlas places it where antibodies can reach.
Gene: Protein-coding gene on chromosome 20 (23,065,139 to 23,086,324, reverse strand). Ensembl gene ENSG00000125810.
Subcellular location: Cell membrane
Subcellular location (Human Protein Atlas): Plasma membrane; Vesicles
Pathways (Reactome):
Immune System: Neutrophil degranulation
Gene Ontology:
Molecular function: complement component C1q complex binding; protein binding; signaling receptor activity; calcium ion binding
Biological process: angiogenesis; cell-cell adhesion; macrophage activation; phagocytosis
Cellular component: plasma membrane; ficolin-1-rich granule membrane; secretory granule membrane; specific granule membrane; tertiary granule membrane; cell surface; cytoplasmic vesicle
Genetic constraint (gnomAD): Loss-of-function variants: 43 observed, 44.81 expected, observed/expected ratio (o/e) 0.96, 90% interval 0.75 to 1.24. The upper end of that interval is the gene's LOEUF score, 1.24, which puts it in group 5 of 6, group 1 being the genes least tolerant of losing a copy. Missense variants: 916 observed, 854.62 expected, observed/expected ratio (o/e) 1.07, 90% interval 1.01 to 1.13. Synonymous variants: 430 observed, 374.7 expected, observed/expected ratio (o/e) 1.15, 90% interval 1.06 to 1.24.
Homologues: Orthologues: chimpanzee CD93 (98% identical), macaque CD93 (95% identical), rabbit CD93 (74% identical), pig CD93 (72% identical), dog CD93 (71% identical), mouse Cd93 (68% identical), rat Cd93 (67% identical), guinea pig CD93 (65% identical), tropical clawed frog CD93 (35% identical), zebrafish cd248a (30% identical), zebrafish cd248b (27% identical), Caenorhabditis elegans ZK1193.2 (17% identical), and 7 more. Paralogues in human: CD248 (26% identical), DLL3 (17% identical), CLEC14A (16% identical), CRELD1 (15% identical), FBLN7 (15% identical), CRELD2 (14% identical), DLK2 (14% identical), WIF1 (13% identical).
Diseases named in the same sentence as CD93 in open-access papers:
CD93 is named in the same sentence as 115 diseases in open-access papers, as found by Europe PMC text mining. Sharing a sentence is not in itself a finding about the gene and the disease. The quoted sentences say what the papers report.
leukemia (14 papers, 2017 to 2025). A malignant (clonal) hematologic disorder, involving hematopoietic stem cells and characterized by the presence of primitive or atypical myeloid or lymphoid cells in the bone marrow and the blood. "Among the genes with significant changes upon TMIGD2 depletion were factors closely associated with cell-cycle (CDKN1A and CCND1) and leukemia stemness (CD93 and IL1RAP)." (PMID 38167704, 2024). "CD93 signaling is a leukemia stem cell-specific regulator of self-renewal and proliferation and a targetable pathway to eliminate leukemia stem cells in chronic myeloid leukemia." (PMID 36761750, 2023). "High CD93 levels were also found correlated with poor survival and increased proliferation capacity in leukemia." (PMID 35242761, 2022). "Specifically, the differentially expressed gene RAS oncogene family like 6 (RABL6, also known as RBEL1 and C9orf86), CD93, and Zinc Finger Protein 709 (ZNF709) have been implicated in cancers and leukemia." (PMID 32134197, 2020). "Another interesting study described the association between high expression of CD93 and loss of CDKN2B (p15Ink4b) expression; a cell-cycle inhibitor gene that has been shown to play a prominent role in leukemia pathogenesis and correlate with poor prognosis." (PMID 28646224, 2017). "Thus, we can see that our LSC, P11, showed to be beneficial as a model for CD47 and CD93 therapeutic research, while additional leukemia lines are needed to represent the pleura of AML subtypes fully." (PMID 36765677, 2023). "Various surface markers, such as CD93, CD69, and CD36, have been found to demarcate distinct subpopulations of immunophenotypically sorted HSC-like cells (CD34+CD38−) that differ in leukemia initiating activity and cell cycle status." (PMID 37653425, 2023). "They observed that CD93 was expressed on a significant percentage of cells in the LSC fraction of MLL-rearranged leukemia, while this marker was negative on LSC subpopulations within non-MLL leukemia and normal cord blood cells." (PMID 28646224, 2017). "CD93, an AML with MLL rearrangements marker expressed on leukemia stem cells (LSC), may also be a useful therapeutic target candidate for anti-LSC therapy and prognostic marker for quantitation of minimal residual disease." (PMID 28646224, 2017). "Taken together, these in vitro and in vivo results suggest that the CD93+ population represents a more primitive self-renewing population of CP-CML LSCs than CD93− cells and is a more immature precursor population within the leukemia stem and progenitor cell hierarchy." (PMID 31896780, 2020).
glioma (11 papers, 2018 to 2026). A benign or malignant brain and spinal cord tumor that arises from glial cells (astrocytes, oligodendrocytes, ependymal cells). "In gliomas implanted in CD93-deficient mice, β1 integrin activation in tumor vasculature was impaired, preventing fibronectin from forming fibrous structures." (PMID 40943530, 2025). "An interesting study found that CD93 protein and gene expression was increased in tumor-associated blood vessels of human glioma compared with that in a normal brain." (PMID 37443812, 2023). "Association analyses between CD93 and gliomas-infiltrating immunocytes indicated that the infiltrating degrees of most immunocytes exhibited positive correlations with CD93, particularly these immunosuppressive subsets such as TAM, Treg, and MDSCs." (PMID 36006582, 2022). "Elucidating the specific mechanism underlying the function of CD93 in glioma-associated immunosuppression remains a challenge." (PMID 36006582, 2022). "Subsequent association analysis documented the predominant role of CD93 among glioma-relevant immunobiological processes and also inflammatory responses." (PMID 36006582, 2022). "We also observed that growth of orthotopically implanted syngeneic GL261 glioma was inhibited in CD93–/– mice, and that this was associated with decreased tumor vessel functionality." (PMID 29763414, 2018). "Thus, further analyses examining the association between CD93 and glioma-infiltrating immunocytes are indispensable." (PMID 36006582, 2022). "What is interesting among these results is that CD93 involves in glioma-associated immune responses such as leukocyte migration, which may play a role in the immune microenvironment of gliomas." (PMID 36006582, 2022). "CD93 deficiency could significantly induce defects in interendothelial junctions, increased permeability and decreased perfusion of the glioma vasculatures." (PMID 36006582, 2022). "Consequently, tumor vessels in gliomas implanted orthotopically in CD93-deficient mice showed diminished activation of β1 integrin and lacked organization of fibronectin into fibrillar structures." (PMID 29763414, 2018). "Similarly, CD93 deficiency reduced β1 integrin activation in murine GL261 glioma tumor vessels in vivo." (PMID 29763414, 2018). "Moreover, association analyses examining CD93 and glioma-infiltrating immunocytes indicated that the degree of infiltration of most immunocytes exhibited positive correlations with CD93 expression, particularly in immunosuppressive subsets such as TAM, MDSCs, and Tregs." (PMID 36006582, 2022). "Using a GL261 glioma mouse model, they showed CD93 was predominantly expressed in glioma vasculature, with stronger staining in tumor blood vessels than in surrounding brain tissue." (PMID 40943530, 2025). "In female mice, CD93 deletion delayed GL261 glioma growth and enhanced survival compared to wild-type mice, linked to increased permeability and reduced perfusion of glioma vasculature." (PMID 40943530, 2025). "Similar to our previous observations in glioma and fibrosarcoma models, HCmel12 tumor growth was significantly decreased in CD93–/– mice as compared with wild-type mice." (PMID 38441970, 2024). "Prognostically, higher CD93 expression levels were correlated with worse oncologic outcomes in kidney renal papillary carcinoma, glioma, ovarian cancer, and uveal melanoma." (PMID 38468017, 2024). "Further, investigating CD93 function in glioma, Lugano and colleagues confirmed that CD93 expression was increased in tumor vessels of high-grade glioma." (PMID 37443812, 2023). "First, we studied the corresponding RNA-seq information from these glioma cases in both sets to investigate the CD93-expression status." (PMID 36006582, 2022). "Kaplan–Meier curves together with multivariable Cox analyses upon survivance identified high-expression CD93 as a distinct prognostic variable for glioma patients." (PMID 36006582, 2022).
glioma (continued). "CD93 was actively involved in the regulation of pathologic angiogenesis, vessel architecture and vascular function for gliomas." (PMID 36006582, 2022). "Here, we methodically investigated CD93 in the context of glioma from its expression patterns, pathobiological roles, and prognosis, particularly the characteristics of glioma-relevant immunosuppressive responses together with immunocyte infiltration degrees." (PMID 36006582, 2022). "For the TCGA database, the area under the curve reached 0.892 when CD93 predicted gliomas of the mesenchyme subform." (PMID 36006582, 2022). "Previous reports have confirmed the significance of CD93 in the progression of multiple tumors; however, there are few studies examining its immune properties for gliomas." (PMID 36006582, 2022). "Briefly, our explorations primarily investigated CD93 expression patterns, biological functions, and clinical value in the context of glioma." (PMID 36006582, 2022). "Our exploration provides strong practical evidence for the CD93-targeted tactics of glioma-based precise diagnosis and therapies." (PMID 36006582, 2022). "Based on the expression status and survival characteristics along with the known biologic functions of CD93 among gliomas, we conceived CD93 as a practicable marker and a promising target for glioma-relevant precise diagnosis and therapeutic strategies." (PMID 36006582, 2022). "CD93 was remarkably overexpressed in gliomas classified as high WHO grades, particularly among patients with GBM in both cohorts." (PMID 36006582, 2022). "These inspiring explorations reveal the potential involvement of CD93 in glioma-connected immunosuppression along with invasion." (PMID 36006582, 2022). "GO analysis of CD93 documented its predominant part in glioma-related immunobiological processes and inflammation responses." (PMID 36006582, 2022). "We observed that CD93 expression levels are markedly upregulated in glioma patients with high grade tumors." (PMID 36006582, 2022). "CD93 is a transmembrane receptor that is upregulated in tumor vessels in many types of cancer, including high-grade glioma." (PMID 33828969, 2021). "CD93 is a transmembrane receptor that is upregulated in tumor vessels in many cancers, including high-grade glioma." (PMID 29763414, 2018). "In vivo, the fibronectin fibrillary network associated with the vasculature was disrupted during tumor angiogenesis in GL261 gliomas implanted intracranially in CD93–/– mice." (PMID 29763414, 2018). "Among these genes, we identified the single-pass transmembrane glycoprotein CD93 as significantly upregulated in glioblastoma vessels compared with vessels in low-grade glioma and in normal brain." (PMID 29763414, 2018). "MMRN2 was expressed in CD31-positive tumor vessels of human glioblastoma (grade IV glioma), colocalizing with CD93 expression." (PMID 29763414, 2018). "Consistent with this, the fibronectin network connected to the tumor vasculature is disrupted in intracranially implanted gliomas in CD93–/– mice." (PMID 29763414, 2018). "Gliomas with high vascular expression of CD93 express higher levels of MMRN2 and show enhanced fibronectin deposition." (PMID 29763414, 2018). "CD93 is highly expressed in the tumor vasculature of human high-grade gliomas as well as in tumor vessels in the orthotopic murine GL261 glioma model." (PMID 29763414, 2018). "They found CD93 positivity in the blood vessels of 73% of grade IV glioma samples, particularly in the tumor core and invasive front, with vascular CD93 expression correlating with glioma grade." (PMID 40943530, 2025). "In histologic and immunofluorescent analyses, gliomas in CD93 KO mice were infiltrated by endothelia with abnormally polarized lumens and increased vascular permeability compared to controls, suggesting a high degree of vessel dysfunction in the absence of CD93." (PMID 38468017, 2024).
glioma (continued). "Moreover, intracranial growth in the GL261 mouse model of glioma was reduced in CD93−/− host mice, improving survival compared with wild-type mice." (PMID 37443812, 2023). "Moreover, CD93 expression was correlated to the tumor grade with a maximum expression in grade IV glioma (glioblastoma) vessels, suggesting a key role of CD93 tumor vascularization." (PMID 37443812, 2023). "In addition, researchers have found a reduced VEGF-induced tube formation in endothelial cells when CD93 was silenced, demonstrating the key role of CD93 in glioma angiogenesis and vascular function." (PMID 37443812, 2023). "We anticipate that CD93-targeting treatments, either individual or in combination with comprehensive therapies, will become a consequential tactic for combined and individual precise therapies for glioma." (PMID 36006582, 2022). "Additionally, CD93 has been demonstrated to exhibit favorable applicability in regard to estimating mesenchyme subform gliomas." (PMID 36006582, 2022). "Based on the recognized clinical significance of these molecular pathological subforms for glioma, glioma patients with elevated CD93 expression in tumor tissue may possess a high probability of neoplasm invasion, local recurrence, and treatment insensitivity." (PMID 36006582, 2022). "Moreover, we further investigated the role of CD93 in the overall prognosis of glioma patients interconnected with certain major clinical variables such as sex, age, WHO grades, and MGMT promoter methylation status." (PMID 36006582, 2022). "Subsequently, we explored the relationship between CD93 and the prognosis of glioma patients." (PMID 36006582, 2022). "Moreover, CD93 was also involved in the matrix organization for ECs in vascularization processes of gliomas." (PMID 36006582, 2022). "Second, we separately analyzed the impact of CD93 on the OS rate for patients with low-grade gliomas (LGG) as well as patients with HGG to avoid the effects of heterogeneous differences in various tumoral grades, and we determined that the impact of CD93 on OS was more apparent for HGG patients." (PMID 36006582, 2022). "In the future, CD93 is expected to be applied for molecule-integrated diagnosis, comprehensive therapeutics, and fluorescence molecule imaging during operations and in the construction of targeted drug carriers for glioma." (PMID 36006582, 2022). "CD93 is markedly associated with adverse pathology types, unfavorable survival, and immunosuppressive immunocytes infiltration among gliomas, thus identifying CD93 as a practicable marker and a promising target for glioma-based precise diagnosis and therapeutic strategies." (PMID 36006582, 2022). "Thus, we compared the variance in the mRNA levels of CD93 among the molecular pathological types of gliomas." (PMID 36006582, 2022). "The interaction between CD93 and multimerin-2 (MMRN2) delivers integrin-dependent signals to regulate Src activation, fibronectin deposition, endosialin loss and prevent the development of fibrosis in ECM during glioma angiogenesis." (PMID 36006582, 2022). "However, no defects were reported in pericyte coverage of vessels in models of gliomas between CD93 knockout and wild‐type mice." (PMID 31287944, 2019). "For gliomas, CD93 is currently considered as a possible therapeutic target since CD93-targeted therapy could significantly inhibit the growth and vascular perfusion of glioma in vivo by decreasing tumoral angiogenesis and repairing integrity of endothelial tight junctions." (PMID 36006582, 2022). "In light of these reports and together with our observations, CD93-targeting therapy is likely to supplement the present therapeutic tactics for glioma, whether administered singly or in combination with immunotherapies, and it could also be used in the context of anti-angiogenesis therapeutics." (PMID 36006582, 2022).